REN (renin)
Diseases named in the same sentence as REN in open-access papers (continued):
Sharing a sentence is not in itself a finding about the gene and the disease.
heart failure (continued). "These factors possibly contribute to the decrease in apelinergic expression in heart failure, which includes myocardial stretch and activation of the renin-angiotensin and aldosterone systems." (PMID 37779742, 2023). "Nonsteroidal anti-inflammatory drugs (NSAIDs), diuretics, and renin–angiotensin system inhibitors (RASis) are common medications for ischemic cardiovascular diseases and heart failure." (PMID 37754834, 2023). "The main effect of valsartan is to inhibit the activation of the renin-angiotensin-aldosterone system and improve the long-term prognosis of patients with heart failure." (PMID 35222898, 2022). "This is consistent with the well-established activation of the renin-angiotensin system and the sympathetic nervous system in heart failure." (PMID 35103864, 2022). "Heart failure promotes the neurohormonal activation of the sympathetic nervous system and the renin-angiotensin-aldosterone system (RAAS), which plays a critical role in the regulation of cardiovascular processes." (PMID 35126818, 2022). "Patients with DCMP have overactivation of the renin-angiotensin-aldosterone systems, which can also adversely affect myocardial metabolism in heart failure." (PMID 35033178, 2022). "Targeting the renin–angiotensin–aldosterone system, on the other hand, has been well studied in the heart failure population with therapies focusing on neurohormonal blockade as the standard of care for these patients." (PMID 35743613, 2022). "Nowadays, sacubitril-valsartan has accounted for 63.7% of the renin-angiotensin-aldosterone system inhibitors in patients with HF in the report 2020 Clinical Performance and Quality Measures for Heart Failure in China." (PMID 36062091, 2022). "Combined neprilysin inhibitor/renin‐angiotensin blockade reduced death from boh worsening heart failure and sudden cardiac death and heart failure hospitalization compared with a renin‐angiotensin blocker alone." (PMID 35789017, 2022). "Drugs that target various components of the systemic RAS, including angiotensin ii type 1 receptor blockers (ARBs), renin inhibitors, and angiotensin converting enzyme inhibitors, are used to treat heart failure." (PMID 36401332, 2022). "The sympathetic nervous system (SNS) and the renin-angiotensin-aldosterone system (RAAS) are intimately associated with morbidity and death with the progression of heart failure." (PMID 36712264, 2022). "The renin-angiotensin-aldosterone system (RAAS) is an important mediator in the pathophysiology of heart failure." (PMID 36017290, 2022). "In case of heart failure, first-line therapy includes salt restriction and agents that target the renin–angiotensin–aldosterone-system combined with β-blockers in low doses if necessary to achieve BP control." (PMID 35628624, 2022). "In heart failure, there is activation of the renin–angiotensin system which plays an active role in the remodelling of the heart and in fluid and electrolyte imbalance which are compensatory initially but eventually leads to worsening of the condition." (PMID 35309046, 2022). "Symptomatic heart failure with reduced ejection fraction (HFrEF) is characterized by edema and chronic pathological activation of the classical renin–angiotensin–aldosterone system (RAAS)." (PMID 36009420, 2022). "During any acute heart failure episode or further decompensation, the renin‐angiotensin system becomes activated resulting in elevated plasma neurohormone concentrations." (PMID 35861811, 2022). "The drugs that are presently used for the treatment of heart failure aim to suppress the functionality of the renin-angiotensin and sympathetic nervous systems." (PMID 35173540, 2022). "The guideline-directed medical treatment recommended for all patients with decompensated heart failure includes diuretics, beta-blockers, renin-angiotensin system inhibitors (ACE inhibitor/ARB), and mineralocorticoid-receptor antagonists." (PMID 34824941, 2021).
heart failure (continued). "More heart failure medications including renin-angiotensin-aldosterone system blockade and diuretics were used by patients with CV outcomes compared to those without CV outcomes." (PMID 34395565, 2021). "Renin–angiotensin–aldosterone system inhibitors (RAASi) reduce morbidity and mortality in heart failure (HF) with reduced ejection fraction in a dose-dependent manner." (PMID 33599908, 2021). "Heart failure guidelines are based around inhibition of the renin-angiotensin and sympathetic nervous systems, two fundamental pathways which drive the pathophysiology of HFrEF using ACE inhibitors (ACEi) and beta-blockers." (PMID 33653703, 2021). "For all patients with heart failure with an ejection fraction less than 40%, Renin-angiotensin system inhibitor, in addition to beta-blocker, is recommended to reduce hospitalization due to heart failure or premature death." (PMID 34949192, 2021). "Renin-angiotensin system inhibitors (RASi) are widely utilized in the area of cardiovascular disease including heart failure and myocardial infarction and revealed the ability to reverse left ventricular (LV) remodeling." (PMID 34275476, 2021). "In most patients, heart failure arises from complex interactions between pre-existing conditions, cardiac injury, renin-angiotensin system activation, and the effects of systemic inflammation on the cardiovascular system." (PMID 33791346, 2021). "Fourth, the benefit of apabetalone on heart failure events was observed on a background of high utilization of beta-blockers and renin-angiotensin system inhibitors, agents demonstrated to be beneficial in heart failure." (PMID 33413345, 2021). "TRANSLATIONAL OUTLOOK 2: Our data suggests a significant 30-day survival benefit with efficient renin-angiotensin blockade prior to surgery in advanced heart failure patients undergoing heart transplant or LVAD surgery." (PMID 35076588, 2021). "Renin-angiotensin system inhibitors (RASi) are widely utilized in the area of cardiovascular disease including heart failure, myocardial infarction, and so on due to the ability to reversing the left ventricular remodeling." (PMID 34275476, 2021). "Alternatively, previous reports have suggested that neurohumoral activation, such as that of the renin angiotensin aldosterone system and sympathetic nervous activation, exacerbates cardiac function, leading to poor prognosis in heart failure patients." (PMID 34255808, 2021). "For example, heart failure, an important risk factor of contrast media induced kidney injury, may through reduced cardiac output and venous congestion reduce perfusion of the kidneys, thus, activating renin-angiotensin-aldosterone-system (RAAS) and trigger a proinflammatory state." (PMID 34925697, 2021). "The renocardiovascular link provided by the sympathetic efferents and the renin-angiotensin system turns out operational in essential hypertension, heart failure, CDK, and obesity/metabolic syndrome." (PMID 34757495, 2021). "At 3-month follow-up, the mean percentage of the target dose for heart failure medication regarding beta-blocker, Renin-angiotensin system inhibitors, and mineralocorticoid receptor antagonists was higher than at prescription for all named medications." (PMID 34883802, 2021). "Rationale: The compensatory activation of the renin-angiotensin system (RAS) after myocardial infarction (MI) plays a crucial role in the pathogenesis of heart failure." (PMID 33664858, 2021). "The effect of combination therapies with beta blockers and inhibitors of the renin-angiotensin system for the treatment of heart failure highlights the importance of the SNS and the kidney." (PMID 34757495, 2021). "The process of heart failure is connected with the renin–angiotensin–aldosterone system (RAAS) activation, which contributes to increased synthesis of angiotensin II." (PMID 34356987, 2021). "Heart failure patients have multiple neurohormonal abnormalities and disturbed renin-angiotensin axis." (PMID 32894050, 2020).
heart failure (continued). "Abnormal function is well documented of both the osmoregulatory system and the renin-angiotensin-aldosterone system in heart failure, liver disease, and chronic renal disease." (PMID 33343937, 2020). "To overcome this concern, we generated a heart failure animal model overexpressing human renin and human angiotensinogen by breeding CSQ‐tg mice with RA‐tg mice." (PMID 32056390, 2020). "Renin is the rate‐limiting enzyme of the renin–angiotensin system cascade, which drives the pathophysiological progression of heart failure." (PMID 32056390, 2020). "Heart failure activates a variety of systemic compensatory stress responses, including stimulation of the sympathetic catecholamine system, the renin angiotensin aldosterone system and other systems." (PMID 32498720, 2020). "A previous study demonstrated that Ang II-mediated exosome secretion from HCF regulated heart failure progression via up-regulation of the renin-angiotensin system." (PMID 31167519, 2019). "Heart failure (HF) progression is affected by various pathways, including the sympathetic nervous system, the renin-angiotensin-aldosterone system (RAAS), and the natriuretic peptide (NP) system." (PMID 31404946, 2019). "Traditionally, patients with heart failure have been treated with a beta-blocker in addition to an inhibitor of the renin-angiotensin-aldosterone system." (PMID 31672170, 2019). "Recently, it has been documented that use of renin–angiotensin–aldosterone system inhibitors has been shown to delay the progression of CKD and risk of heart failure and death." (PMID 30617956, 2019). "In heart failure patients, activation of the renin–angiotensin–aldosterone system is known to induce hypokalemia." (PMID 31087220, 2019). "Heart failure is a complex clinical syndrome involving a multitude of neurohormonal pathways including the renin-angiotensin-aldosterone system, sympathetic nervous system, and natriuretic peptides system." (PMID 30959745, 2019). "Its mechanism is due to the release of inflammatory mediators whilst heart failure, the activation of renin-angiotensin system." (PMID 30139350, 2018). "The renin-angiotensin-aldosterone system (RAAS) is activated by arterial underfilling caused by CPB, heart failure, shock and so on after cardiac surgery." (PMID 30107786, 2018). "H2S also improve ISO-induced heart failure by inhibiting mast cell infiltration and renin degranulation to inhibit local renin levels." (PMID 30298008, 2018). "The renin-angiotensin system (RAS) plays an essential role in the pathophysiological progression of heart failure, which involves cardiac hypertrophy, apoptosis, and ventricular dilation." (PMID 30092100, 2018). "The renin‐angiotensin system promotes oxidative stress, apoptosis, necrosis, fibrosis, and thus heart failure." (PMID 30247805, 2018). "Since it is considered that these AEs were caused by an excess dual RAS blockade with high doses of its inhibitors including renin inhibitor, they should be used as monotherapy in heart failure patients with systolic dysfunction." (PMID 30092100, 2018). "The renin-angiotensin system (RAS), which plays an important role in the progression of heart failure, is efficiently blocked by the inhibition of renin, the rate-limiting enzyme in the RAS cascade." (PMID 30092100, 2018). "Brain renin-angiotensin system and oxidative stress have already been established to induce sympathoexcitation in heart failure." (PMID 29495326, 2018). "The MEK/ERK1/2 signaling plays an important role in the regulation of the renin-angiotensin system toward the sympathetic nervous system, in the brain of heart failure rats." (PMID 28210225, 2017). "In the setting of heart failure, hyponatremia reflects more severe activation of the renin–angiotensin–aldosterone and of the sympathetic nervous system as well as increased vasopressin release." (PMID 28212578, 2017).
heart failure (continued). "Renin-angiotensin-aldosterone system (RAAS) activation plays a crucial role in the pathophysiologic changes of heart failure." (PMID 29152151, 2017). "Many of the published genetic studies of heart failure have been candidate gene studies for genes involved in the adrenergic and renin-angiotensin-aldosterone pathways that are important for heart failure pathobiology." (PMID 28228157, 2017). "Reduced tissue perfusion is largely caused by the compensatory activation of the sympathetic nervous system and the renin-angiotensin-aldosterone system, which lead to a reduction in cardiac output in patients with heart failure." (PMID 29021616, 2017). "Our findings do not support the role of direct renin inhibitor aliskiren as a favourable drug for heart failure patients who have received optimal medications, although some studies do show that it decreases plasma renin concentration and activity." (PMID 29152151, 2017). "For preserving the reduced systolic function of the heart, the renin–angiotensin–aldosterone system (RAAS) is activated during the early period of heart failure." (PMID 26986475, 2016). "Referring to the heart failure patients there has to be recognized an episode of severe stress resembled by well-known activation of neuro humeral axis, release of renin, cortisol and norepinephrine." (PMID 27861527, 2016). "Inhibition of the renin–angiotensin system (RAS) via angiotensin-converting enzyme (ACE)-inhibitors is the main treatment for heart failure." (PMID 26871774, 2016). "Blocking the renin-angiotensin-aldosterone system in ST-elevation myocardial infarction (STEMI) patients prevents heart failure and recurrent thrombosis." (PMID 27064499, 2016). "Studies demonstrate that neurohumoral activation plays an important role in the development of heart failure after myocardial infarction, including the renin-angiotensin-aldosterone system (RAAS) and the sympathetic nervous system." (PMID 27843475, 2016). "Suppression of the renin–angiotensin system (RAS) by angiotensin-converting enzyme (ACE)-inhibitors remains the mainstay of treatment for heart failure." (PMID 26871774, 2016). "Increased circulating levels of angiotensin II and elevated plasma renin activity occur with the development of severe heart failure in patients." (PMID 26509155, 2015). "The activation of renin-angiotensin system (RAS) is a significant risk factor for the development of arterial hypertension, LVH, and heart failure." (PMID 26509155, 2015). "We would like to emphasis that excess circulating angiotensin II would be one of the major sympathoexciting factors via central renin-angiotensin system in myocardial infarction-induced heart failure." (PMID 26290529, 2015). "Activation of central PPAR gamma reduces sympathetic excitation and improves peripheral manifestations of heart failure by inhibiting brain renin-angiotensin system activity." (PMID 25414671, 2014). "The hyperaldosteronism developed by the SHHF rats makes this model appropriate to study the influence of the renin angiotensin aldosterone system on heart failure progression." (PMID 24831821, 2014). "The RAS has been an important drug target for therapeutic intervention: Ang II receptor blockers (ARBs), angiotensin converting enzyme inhibitors (ACEi) and renin inhibitors reduce heart failure-related morbidity and mortality." (PMID 26237391, 2014). "PPAR gamma regulates the renin-angiotensin system activity in the hypothalamic paraventricular nucleus and ameliorates peripheral manifestations of heart failure." (PMID 25414671, 2014). "Resistant hypertension has the similar pathophysiologic mechanism to heart failure, as the excessive activation of renin-angiotensin-aldosterone system and sympathetic nervous system." (PMID 25490405, 2014). "The pathophysiological mechanisms of heart failure (HF) stems were mainly from longstanding overactivation of the sympathetic nervous system and renin-angiotensin-aldosterone system." (PMID 25187901, 2014).
heart failure (continued). "The RAAS is activated later in the course of heart failure with the possible mechanisms of the renal hypoperfusion due to low cardiac output and the increased renin release due to sympathetic stimulation of the kidney." (PMID 22935019, 2012). "Two of the most important regulatory systems in heart failure, the natriuretic peptide axis and the renin-angiotensin-aldosterone system (RAAS), are considered examples of critical functional modules." (PMID 22935019, 2012). "Maladaptive neurohormonal signaling involving the renin-angiotensin-aldosterone and adrenergic systems are fundamental pathophysiological processes in heart failure." (PMID 21359201, 2011). "In heart failure pathogenesis, FXII deficiency and pharmacological inhibition of FXII activity blocked activation of the renin-angiotensin-aldosterone system (RAAS) in dilated cardiomyopathy, increased median survival, and delayed heart failure onset in murine models." (PMID 41683756, 2026). "Heart failure (HF) is a global health challenge characterized by the heart's inability to satisfy metabolic demands, driven by renin-angiotensin-aldosterone system (RAAS) overactivation, a neurohormonal imbalance, and emerging mechanisms like the gut-heart axis and mitochondrial dysfunction." (PMID 41751385, 2026). "During the six-month therapeutic period, the prevalence of heart failure medications remained unchanged in the whole cohort (p = 1.0 for beta-blockers, renin–angiotensin system inhibitors, and mineralocorticoid receptor antagonists; p = 0.50 for sodium–glucose co-transporter 2 inhibitors)." (PMID 40869682, 2025). "Furthermore, supplementation with vitamin D3 has been reported to reduce plasma renin concentrations in individuals with heart failure, highlighting its potential regulatory role in the renin–angiotensin system." (PMID 40941272, 2025). "Since age and heart failure influence the parameters of the renin–angiotensin–aldosterone system, the question arises whether the pharmacodynamics of enalaprilat differ in children with heart failure compared to healthy adults." (PMID 41155980, 2025). "The inability of the diseased kidneys to excrete salt and water, as well as abnormal renin secretion, can increase heart load and promote heart failure; in turn, poor renal perfusion due to lower cardiac output aggravates renal failure, which means renal–heart crosslinking." (PMID 40225592, 2025). "AMI-induced myocardial necrosis and systemic inflammatory responses often result in cardiac dysfunction, heart failure, and renal perfusion deficits, exacerbated by systemic responses such as sympathetic overactivation and renin-angiotensin-aldosterone system upregulation." (PMID 40242450, 2025). "A previous model-independent analysis in ACE inhibitor-naïve children with heart failure from the LENA project showed a significant increase in plasma renin activity at the dose confirmation visit, which took place on average 5 days after the first dose of enalapril." (PMID 41155980, 2025). "Its impact on mortality may arise from venous congestion, forward heart failure, activation of the renin-angiotensin-aldosterone system (RAAS), and sympathetic stimulation associated with heart failure." (PMID 41409749, 2025). "In the Normal/mild-AKI vs. Moderate-severe-AKI group, heart failure impairs cardiac pumping, reducing renal perfusion, triggering renal vasoconstriction, and activating the renin-angiotensin-aldosterone system (RAAS) to induce/worsen AKI, making these patients more prone to moderate-severe AKI." (PMID 40766058, 2025). "Observational clinical evidence suggests that preserved ejection fraction and elevated or normal blood pressure, leading to increased venous pressure, are key contributors to declining eGFR and activation of the renin‐angiotensin‐aldosterone system in the context of heart failure." (PMID 41312157, 2025).